C4orf51 (chromosome 4 open reading frame 51)
Tractability: No criterion of Open Targets' tractability assessment is met for any kind of drug.
Gene: Protein-coding gene on chromosome 4 (145,680,146 to 145,771,032, forward strand). Ensembl gene ENSG00000237136.
Genetic constraint (gnomAD): Loss-of-function variants: 12 observed, 13.04 expected, observed/expected ratio (o/e) 0.92, 90% interval 0.59 to 1.49. The upper end of that interval is the gene's LOEUF score, 1.49, which puts it in group 6 of 6, group 1 being the genes least tolerant of losing a copy. Missense variants: 180 observed, 176.63 expected, observed/expected ratio (o/e) 1.02, 90% interval 0.9 to 1.15. Synonymous variants: 79 observed, 63.65 expected, observed/expected ratio (o/e) 1.24, 90% interval 1.03 to 1.5.
Homologues: Orthologues: chimpanzee C4H4orf51 (99% identical), macaque C5H4orf51 (95% identical), pig C4orf51 (64% identical), mouse 1700011L22Rik (52% identical), rat C19h4orf51 (49% identical).
Diseases named in the same sentence as C4orf51 in open-access papers:
C4orf51 is named in the same sentence as 1 disease in open-access papers, as found by Europe PMC text mining. Sharing a sentence is not in itself a finding about the gene and the disease. The quoted sentences say what the papers report.
breast carcinoma (1 paper, 2020). "Although the NPBWR1, A2ML1 and C4orf51 displayed differential expression, their expression level in breast cancer tissues is still not high, which may be due to their own expression abundance or sensitivity of the detection probe." (PMID 31998560, 2020).